BDNF (brain derived neurotrophic factor)
Diseases named in the same sentence as BDNF in open-access papers (continued):
Sharing a sentence is not in itself a finding about the gene and the disease.
depression (continued). "Luteolin may influence BDNF and its downstream apoptotic proteins such as Bax and Bcl-2 to significantly combat depression." (PMID 30625977, 2019). "Moreover, the elevation of another depression-related parameter i.e., an increase in the hippocampal levels of brain-derived neurotrophic factor (BDNF), was observed." (PMID 31775329, 2019). "Evidence supporting the role of BDNF in depression has been summarized in several meta-analyses." (PMID 31127089, 2019). "Hierarchical regression analyses indicated that approximately 11% of the variance in symptoms of depression could be specifically accounted for by the epistatic interaction of 5-HTTLPR and BDNF val66Met polymorphisms." (PMID 31440532, 2019). "Moreover, it was also found that subchronic As exposure in chemically depression induced mouse model enhances the depression-like behaviors through the cerebral prefrontal cortex BDNF-TrkB signaling pathway." (PMID 31199848, 2019). "After the intervention, there was a significant difference between the treatment groups in increasing the expression level of BDNF (P=0.031), decreasing craving (P=0.000), and decreasing the symptoms of depression (P=0.018), anxiety (P=0.001), and stress (P=0.012)." (PMID 32477481, 2019). "Meta-analyses have shown that BDNF concentrations are lower in patients with depression than in healthy controls and that levels increase with successful antidepressant treatment and/or recovery from depression." (PMID 31572245, 2019). "At the same time, BDNF and TrkB expression in the hippocampus and cortex were downregulated, which might lead to behavioral defects of depression and anxiety." (PMID 31231295, 2019). "All these data support the direct link between losartan, BDNF and depression." (PMID 31053872, 2019). "Treatment with venlafaxine or paroxetine also increased BDNF in patients with depression." (PMID 31231295, 2019). "Brain-derived neurotrophic factor (BDNF) could also reverse the conditioning-induced depression mimicking extinction." (PMID 30923737, 2019). "However, similar to 5-HTTLPR research reviewed above, another set of findings examining the role of BDNF in depression has come to a diametrically opposite conclusion regarding risk and protective properties of Val and Met alleles." (PMID 31440532, 2019). "Depression is a multifactorial disorder reflecting an accumulation of several pathophysiological conditions including neuroinflammation, elevated microglia activation, an imbalance of tryptophan metabolites and altered BDNF levels." (PMID 31749681, 2019). "All of these studies suggest that BDNF and the mediated TrkB signaling pathway may provide new approaches for the treatment of depression." (PMID 31231295, 2019). "The alteration in BDNF-TrkB signaling is believed to be involved in the pathogenesis of depression, which could be targeted therapeutically." (PMID 31881712, 2019). "BDNF/TRKB signaling has been shown to play a key role in depression." (PMID 31481665, 2019). "In addition, the level of brain-derived neurotrophic factor (BDNF) is decreased in individuals with depression." (PMID 32082167, 2019). "It has been speculated that wash-out periods may mask the expected reduced BDNF levels found in depression, as it is been proposed that antidepressants stimulate BDNF synthesis." (PMID 31231276, 2019). "One hypothesis to be tested would be that religiosity might exert its protective effects against depression by increasing cortical neuroplasticity and neuroprotection through BDNF." (PMID 31572245, 2019). "Also, our study demonstrated that FA significantly increased the protein‐expression level of BDNF in mice brain, the predictive biomarker of depression." (PMID 31394019, 2019). "Moreover, the brain-derived neurotrophic factor (BDNF) has been increasingly investigated for depression in animal models." (PMID 30984042, 2019).
depression (continued). "Second, the results suggested that individual differences in risk as measured by symptoms of depression and anxiety may be due to the interaction of specific 5-HTTLPR and BDNF alleles." (PMID 31440532, 2019). "Hence, these findings strengthen the role of BDNF in the development of major depressive disorder in the Malaysian population and therefore serve a potential biomarker for early MDD screening in the future." (PMID 30677092, 2019). "Evidence suggests that L. helveticus may modulate the central NE system and HPA axis to improve cognition, and the central 5-HT system and BDNF expression to reduce depression." (PMID 32009871, 2019). "Stimulating the Dorsolateral Prefrontal Cortex (DLPFC) led to a significant change in increasing the level of BDNF (P=0.031) and reducing the degree of depression (P=0.018), anxiety (P=0.001), stress (P=0.012), and decreased the level of craving (P=0.001) in opioid-addicted patients." (PMID 32477481, 2019). "The link between BDNF and depression is also confirmed at the genetic level." (PMID 31234814, 2019). "Decreased levels of neurotrophic factors including BDNF could contribute to the atrophy of certain limbic structures, including the hippocampus, and the prefrontal cortex, which has been observed in depression patients." (PMID 32082167, 2019). "The level of BDNF was found to be decreased in the hippocampus of patients with depression." (PMID 32082167, 2019). "A similar study also showed that supplementation with Clostridium butyricum could reduce the depression phenotype and reduced BDNF levels in male C57BL/6J mice undergoing the same stress paradigm." (PMID 31749681, 2019). "As a result, major depressive disorder (MDD) was depicted as being secondary to deviant neurogenesis in brain areas that govern emotion and memory, with deviant neurogenesis associated with a decreased expression of BDNF." (PMID 30794585, 2019). "Indeed, BDNF was reported to be sufficient to produce an antidepressant response in behavioral models of depression." (PMID 31057357, 2019). "For this interaction, partial correlation value of −0.338 and semi-partial correlation value of −0.331 indicated that approximately 10.96%–11.42% of the variance in depression could be explained by serotonin-BDNF interaction." (PMID 31440532, 2019). "Increasing the level of BDNF in the brain can play a role in the treatment of depression." (PMID 32009949, 2019). "Brain-derived neurotrophic factor is a neurotrophin synthesized by neurons and glial cells that has been strongly correlated with changes in volume of specific brain areas observed in patients with major depression." (PMID 31231276, 2019). "For example, Curculigoside (CUR), which is extracted from the traditional Chinese medicine Curculigo orchioides Gaertn (Xianmao in Chinese), was reported to facilitate fear memory and ameliorate depression in mice via stimulating the Akt-mTOR signaling pathway and increasing BDNF expression." (PMID 31569393, 2019). "It is currently believed that physical exercise improves depression symptoms may be related to the upregulation of BDNF in brain via exercise-stimulated BDNF release in muscle." (PMID 32116688, 2019). "At present, most of the studies reported BDNF/TrkB signaling pathway as the therapeutic target for depression by the botanicals, which points out the importance of this specific signaling pathway in the pathogenesis of depression." (PMID 31338119, 2019). "Ketamine, an anesthetic with psychedelic proprieties, have been tested in MD patients and animal models, and patients with treatment resistant depression exhibited increased plasma BDNF after a ketamine session only in responders between 4 h after intake until 1 week later." (PMID 31231276, 2019). "Similarly, in a study examining subjects with depression, melatonin safeguarded hippocampal neurons from damage via BDNF or glial cell-derived neurotrophic factor activation." (PMID 31824318, 2019).
depression (continued). "We demonstrate here that PAI-1 plays a key role in depression by a mechanism independent of the tissue-type Plasminogen Activator (tPA) – Brain-Derived Neurotrophic Factor (BDNF) axis, but associated with impaired metabolisms of serotonin and dopamine." (PMID 31610810, 2019). "Interestingly, miR-124 directly targets and modulates the expression of BDNF, which is known to be involved in neurogenesis and it is also involved in the pathophysiology of depression." (PMID 31350592, 2019). "Because most antidepressants have been shown to lower cortisol levels and promote neurotrophic factors, such as BDNF in both major depressive disorder patients and animal models, we first identified the amount of serum corticosterone known to increase with stress in nCTL and nCre mice." (PMID 31771312, 2019). "In 2006, Duman RS proposed the hypothesis of neurotrophic factors in depression, suggesting that BDNF can promote the growth of sudden contact and maintain the survival of neurons." (PMID 32009949, 2019). "In those studies, the BDNF val66met polymorphism was not directly associated with depression, but the met allele conferred higher vulnerability to depression after stressful events, which were in keeping with the present findings." (PMID 31887219, 2019). "Therefore, we aimed to evaluate the serum BDNF levels in the pathogenesis of acne vulgaris patients with depression." (PMID 31234814, 2019). "administration and/or promotion ameliorates adverse effects of stress on hippocampal serotonin, norepinephrine and brain-derived neurotrophic factor and increases hippocampal and prefrontal N-acetyl-aspartate, GABA and glutamate: biomarkers that are associated with depression." (PMID 30955108, 2019). "Likewise, sesquiterpenoids from ginseng root treatment, ameliorate depression-like behaviors induced by LPS by upregulating the BDNF/TrkB Pathway." (PMID 31231295, 2019). "Therefore, they suggested that early pregnancy BDNF is a potential biomarker to predict antepartum depression." (PMID 31199848, 2019). "Moreover, those animals with low sustained serum BDNF levels (called by the authors “vulnerable”) showed a depression-like profile when challenged by minor stressful events." (PMID 31156384, 2019). "The authors concluded that increased BDNF and pro-BDNF may exert a protective effect by minimizing depression severity but were unable to prevent PTSD development." (PMID 31098654, 2019). "In addition to this, the studied population was homogenous in respect to psychiatric diagnosis (only unipolar depression, inpatients sample), as evidence on the comparison of BDNF levels between various psychiatric diseases remains contradicting." (PMID 31127089, 2019). "As 5-HT facilitates BDNF synthesis, the upregulated central 5-HT expression presumably explains the accompanying increase in hippocampal BDNF expression of mice alleviated of depression from L. paracasei intake." (PMID 32009871, 2019). "Numerous clinical studies confirm the involvement of BDNF in the pathophysiology of depression." (PMID 30767081, 2019). "In agreement with the associations between the BDNF Val66Met SNP and depression in men, but not in women, mice with conditional BDNF knockout in the forebrain also displayed gender differences in depression-related behaviors." (PMID 31480771, 2019). "We expected that baseline serum BDNF levels will predict major depression, the BDNF levels should in turn depend on individual clinical characteristics, with patients with major depression disclosing lower baseline levels of serum BDNF when compared to healthy volunteers." (PMID 31231276, 2019). "It will be interesting to investigate whether hypothalamic BDNF's modulation of the HPA axis contributes to the anti‐depression effect in the aged animals whose stress response system becomes less agile and dysfunctional." (PMID 30585393, 2019).
depression (continued). "Furthermore, acne vulgaris patients with depression showed lower serum BDNF levels (10.96 ± 2.12 ng/ml) compared with acne vulgaris patients without depression (13.85 ± 2.47 ng/ml), as well as with healthy control (14.35 ± 2.70 ng/mg; both P < 0.05)." (PMID 31234814, 2019). "It is currently unknown why SOM+ INs are especially vulnerable to major depressive disorder; one hypothesis is that these neurons lack trophic brain derived neurotrophic factor (BDNF) support." (PMID 31212931, 2019). "In conclusion, these results showed that BDNF exon IX promoter methylation levels, serum BDNF protein level, and serum BDNF mRNA level could contribute to the pathophysiology of a major depressive disorder." (PMID 31027379, 2019). "However, few studies have focused on the effect of SiNiSan treatment for depression triggered by early life adversity through the signaling pathway of 5-HT1A receptor/CREB/BDNF." (PMID 30984042, 2019). "Both MDD patients and animal models of depression show a remarkable reduction in serum BDNF levels." (PMID 30117106, 2019). "Furthermore, the correlation between IR and higher BDNF levels identified in the present study is consistent with previous reports showing a mainly protective effect of religiosity in depressive disorders." (PMID 31572245, 2019). "At the same time, restoring BDNF signaling is imperative in depressive disorders." (PMID 31018603, 2019). "In depressed patients, BDNF levels are reportedly reduced and then increases as symptoms decrease with antidepressant treatment, supporting the neurotrophic hypothesis of depressive disorders." (PMID 31572245, 2019). "BDNF has been widely related to the pathogenesis of depression disorders." (PMID 32082151, 2019). "A first hint for a crucial role of distinct BDNF transcripts in control of cortical inhibition, aggressive behavior, or e.g., in the induction of depression was obtained in BDNF mouse models in which one of its promoters had been impaired." (PMID 30319348, 2018). "Taken together, these data suggest that BDNF could be considered as a key therapeutic molecule against depression." (PMID 29961124, 2018). "Reductions in hippocampal BDNF are found in patients with major depression, which may affect neurogenesis." (PMID 30065945, 2018). "This includes the use of BLEV mice for examining potential therapies in various disease models, where dysregulation of BDNF expression is predicted to contribute to the pathology, such as depression, epilepsy, or Alzheimer's, Huntington's, and Parkinson's disease." (PMID 30319348, 2018). "The level of BDNF is decreased in both the serum and brain during the course of major depression, while successful pharmacological antidepressant treatment is effective to recover the level of BDNF to baseline levels in untreated patients suffering from major depression." (PMID 29419799, 2018). "Together these data posit that enhancement of BDNF and mTORC1 signaling lead to prefrontal synaptic formation (synaptogenesis), and reversal of stress- and depression-induced neuronal atrophy and synaptic dysconnectivity are required for efficacious antidepressant treatment." (PMID 30197765, 2018). "In addition, several studies demonstrated that successful treatment of depression and bipolar disorder normalizes peripheral BDNF concentrations, suggesting that BDNF is a possible marker of disease recovery." (PMID 29944703, 2018). "These anti-inflammatory effects were accompanied by normalizing astrocyte function, shown through the decreased expression of p75, but increased BDNF, which may contribute to the improvement of depression-like changes." (PMID 30248907, 2018). "In addition, BDNF plays a role in depressive disorder, which is frequently comorbid with FM; indeed, the serum level of BDNF is altered in patients with depression." (PMID 30285822, 2018).
depression (continued). "More damage might be associated with the reduction of BDNF in brain regions, particularly in the hippocampus, and decreased BDNF availability could also harm to neuronal growth in specific brain structure, which is critically involved in depression." (PMID 30323763, 2018). "Furthermore, the recent meta-analysis study revealed that the BDNF blood level had significantly difference between the healthy subjects and patients with major depression." (PMID 29357818, 2018). "Brain derived neurotrophic factor displays a potential role as a marker of treatment response in patients with major depressive disorder although its effects on mood variations remain unclear." (PMID 30127743, 2018). "Besides, the serum BDNF levels of patients with depression was lower than those of the control group." (PMID 29845025, 2018). "BDNF, a marker for depression, was also reduced in LPS-induced depressed mice." (PMID 29569964, 2018). "Activation of the mechanistic target of rapamycin (mTOR), as well as increased levels of BDNF, may increase long-term potentiation and result in an improvement in the symptoms of depression." (PMID 30034974, 2018). "We found that the CUMS procedures elevated the expression level of HDAC2 and induced the downregulation of acH3K9 protein and BDNF mRNA, which might contribute to the development of depression." (PMID 29636708, 2018). "Our results indicated that GBH can ameliorate depressive-like behaviors, affect the concentration of mood-related hormones, and help to regulate immune/endocrine dysfunction in mice with reserpine-induced depression, likely via activation of the BDNF-CREB pathway." (PMID 30046601, 2018). "Therefore, we selected the BDNF as a target factor to study the mechanism through which MXYS regulates depression." (PMID 30323763, 2018). "In addition, brain-derived neurotrophic factor (BDNF) is downregulated in several areas of the brain in animal models of depression." (PMID 30323739, 2018). "BDNF levels have been proposed to quantitatively measure depression." (PMID 29321655, 2018). "The molecular link between exercise and depression is not well understood but may be partly mediated by increases in neurotrophic growth factors that promote neuroplasticity, particularly BDNF." (PMID 29559928, 2018). "Collectively, the antidepressant effect of acupuncture might be mediated by regulating the DNA methylation and histone modifications of BDNF, which may represent novel biomaker for detection of depression and monitoring severity and antidepressive effects." (PMID 29636708, 2018). "The BDNF Val66Met polymorphism showed no significant influence on the severity of depression in MS patients, though the result was in disagreement with the findings based in the general population." (PMID 29896439, 2018). "Although studies have identified associations between a variety of biomarkers (serotonin, BDNF, cortisol) and depression symptoms and/or clinical outcomes, none have demonstrated sufficient evidence to progress to use in clinical settings." (PMID 29866991, 2018). "In contrast, low BDNF levels and hippocampal atrophy were observed in animal models of depression." (PMID 30622454, 2018). "Increasing BDNF levels may be a significant mechanism of ketamine’s effect on depression since another clinical trial showed direct infusion of BDNF also helped ameliorate depressive symptoms." (PMID 30034974, 2018). "Further research is needed to clarify the precise mechanisms whether the DNA methylation level of BDNF promoter I, promoter II, and promoter IV is involved in the pathogenesis of depression by applying bisulfite sequencing in our future study." (PMID 29636708, 2018). "A simple linear regression revealed that changes in BDNF were significantly associated with changes in BDI and PSQI scores, indicating that those who experienced a greater increase in BDNF also experienced greater improvement in depression and sleep quality." (PMID 29559928, 2018).